SIRT5 (sirtuin 5)
Diseases named in the same sentence as SIRT5 in open-access papers (continued):
Sharing a sentence is not in itself a finding about the gene and the disease.
leukemia (3 papers, 2020 to 2025). A malignant (clonal) hematologic disorder, involving hematopoietic stem cells and characterized by the presence of primitive or atypical myeloid or lymphoid cells in the bone marrow and the blood. "A novel SIRT5 inhibitor named NRD167 was shown to effectively inhibit SIRT5’s demalonylase activity in leukemia cells, causing an increase in protein malonylation and a corresponding block in leukemic growth." (PMID 41107644, 2025). "In mouse models of AML, treatment with SIRT5 inhibitors or genetic ablation of SIRT5 significantly delays leukemia progression and extends survival, confirming that SIRT5 (and, by extension, protein malonylation) is a drug target." (PMID 41107644, 2025). "Analysis of the IVIS spectrum revealed a trend toward a greater leukemia load in the SIRT5-knockdown group than in control mice." (PMID 38485947, 2024). "Notably, the addition of THF to the SIRT5-inhibited leukemia cells reversed the effects of combined histidine and 6-MP treatment on cellular proliferation and apoptosis to levels similar to the control treatment group." (PMID 38485947, 2024). "In addition, leukemia-bearing mice subjected to SIRT5-knockdown exhibited significantly aggravated tumor burden even when treated with histidine and 6-MP." (PMID 38485947, 2024). "Furthermore, HINT1 overexpression re-sensitized SIRT5 knocked down leukemia cells to 6-MP in the presence of histidine." (PMID 38485947, 2024). "Moreover, it is crucial to note that the introduction of THF in SIRT5-knockdown mice completely nullified the therapeutic effectiveness of the histidine and 6-MP combination treatment against leukemia." (PMID 38485947, 2024). "Consistent with previous results, flow cytometry confirmed that SIRT5 inhibition significantly counteracted histidine and 6-MP-mediated disease control and enhanced the human CD19+ leukemia frequencies in the peripheral blood, bone marrow, and spleen." (PMID 38485947, 2024). "Collectively, these results announced that upregulation of SIRT5 combined with THF utilization accounts for the inhibitory effects of the combined 6-MP and histidine treatment on leukemia cells, and that enzymatic activity is essential for SIRT5 to be effective." (PMID 38485947, 2024). "Additionally, we screened their effect on the enzymatic activity of the histone deacetylase sirtuin family (SIRT1, SIRT2, SIRT3, SIRT5 and SIRT6) using both recombinant enzymes and nuclear lysates from leukemia cells." (PMID 32587297, 2020).
liver disease (3 papers, 2021 to 2024). "Although significant associations between the PNPLA3 GG carriage and MASLD have been documented in several studies, studies regarding the association between the SIRT5 rs12216101 variant and advanced liver disease in patients with MASLD are scarce." (PMID 39596570, 2024). "More recently, SNPs at the SIRT5 gene locus have been identified as a new risk factor associated with advanced liver disease in European patients with MASLD." (PMID 39596570, 2024). "Although SIRT5 has been implicated in a variety of liver diseases, its specific role and underlying mechanisms in AILI have not been well elucidated." (PMID 39159058, 2024). "Additionally, the SIRT5 variant was associated with more severe histological features of liver disease, such as inflammation, steatohepatitis, and significant fibrosis in the Western population with MASLD." (PMID 39596570, 2024). "In an animal model, the over-expressed intrahepatic SIRT5 protein was linked to mitochondrial dysfunction and upregulated pro-inflammatory mediators, leading to the activation of fibrogenesis and advanced steatotic liver disease." (PMID 39596570, 2024). "Sirtuins 5 (SIRT5) has been implicated in the development of various liver diseases." (PMID 39159058, 2024). "Thus, combining assays of the PNPLA3 and SIRT5 GG genotypes as genetic risk factors may have clinical applications, as they could permit the discrimination of patients with a high likelihood of developing severe liver disease." (PMID 39596570, 2024).
lung adenocarcinoma (3 papers, 2021 to 2025). A carcinoma that arises from the lung and is characterized by the presence of malignant glandular epithelial cells. "In EGFR-mutant lung adenocarcinoma, SIRT5 suppresses CD8+ T-cell recruitment through an ACAT1–NRF2 succinylation axis, providing an additional layer of suppression that limits responsiveness to checkpoint blockade." (PMID 41425553, 2025). "Furthermore, a APCDD1L-AS1-miR-1322/miR-1972/miR-324-3p-SIRT5 axis has been investigated to facilitate icotinib-resistance by suppressing autophagic degradation of EGFR in lung adenocarcinoma." (PMID 35350778, 2022). "Additionally, it has been documented that a APCDD1L-AS1-miR-1322/miR-1972/miR-324-3p-SIRT5 axis facilitated icotinib-resistance by suppressing autophagic degradation of EGFR in lung adenocarcinoma." (PMID 35350778, 2022).
osteosarcoma (3 papers, 2016 to 2022). A usually aggressive malignant bone-forming mesenchymal neoplasm, predominantly affecting adolescents and young adults. "However, the aberrant expression of SIRT5 regulated by miRNAs was not implicated with osteosarcoma until our study." (PMID 27990096, 2016).
age (2 papers, 2020 to 2022). A temporal measurement of the time period elapsed since an identifiable point in the life cycle of an organism. "In addition, it was reported that the activity of NAD+ by increasing the SIRT5 protein level contributes to a broad range of age-related pathophysiologies." (PMID 36536955, 2022).
apical periodontitis (2 papers, 2022 to 2024). "In periapical periodontitis, the expression of Sirt5 was reduced along with an increase of oxidative stress and bone lining cell apoptosis, which could be reversed by exogenous Sirt5." (PMID 38709288, 2024). "This led the researchers to conclude that increasing SIRT5 may potentially be a therapeutic treatment for apical periodontitis." (PMID 35630070, 2022).
atherosclerosis (2 papers, 2011 to 2024). A disease characterized by the build-up of fatty material and calcium deposition in the arterial wall resulting in partial or complete occlusion of the arterial lumen. "In this study we report on the association of the UCP5, SIRT6 and SIRT5 gene variants with carotid plaque, a surrogate marker of atherosclerosis." (PMID 22087257, 2011). "However, the gain-of-function SIRT5 rs12216101 polymorphism was linked to enhanced sirtuin activity, which led to susceptibility to cardiometabolic disorders, such as developing carotid plaque, a surrogate marker of atherosclerosis." (PMID 39596570, 2024). "This may interact with the SIRT3 and SIRT5, which are mitochondrial SIRTs, in controlling ROS production and therefore the development of atherosclerosis." (PMID 22087257, 2011).
bacteremia (2 papers, 2018 to 2019). "Together with the fact that SIRT3−/− and SIRT5−/− mice are susceptible to bacterial sepsis like wild-type mice, these observations strengthen the development of pharmacological modulators of the activity of mitochondrial sirtuins for clinical purposes." (PMID 31632409, 2019).
brain injury (2 papers, 2021 to 2025). Acute and chronic (see also brain INJURIES, CHRONIC) injuries to the brain, including the cerebral hemispheres, CEREBELLUM, and brain STEM. "Microglia-specific forced overexpression of SIRT5 worsened ischemic brain injury, while the downregulation of SIRT5 exhibited neuroprotective and cognitive-preserving effects against ischemic brain injury." (PMID 40724883, 2025).
cardiac ischemia (2 papers, 2021 to 2025). "The authors demonstrated that SIRT5 activity is positively correlated with a reduction in fibrosis and an enhancement in cardiac function, while an increased susceptibility to cardiac ischemia–reperfusion injury is associated with SIRT5 downregulation." (PMID 39215785, 2025).
cerebral infarct (2 papers, 2022 to 2023). "Our research revealed that microglia-specific SIRT5 knockdown decreased the cerebral infarction volume and the nerve dysfunction scores." (PMID 36517900, 2022). "The results demonstrated that Tat‐SIRT5‐CTM successfully reduced the cerebral infarct size." (PMID 38093788, 2023).
cholangiocarcinoma (2 papers, 2019 to 2023). A carcinoma that arises from the intrahepatic biliary tree (intrahepatic cholangiocarcinoma) or from the junction, or adjacent to the junction, of the right and left hepatic ducts (hilar cholangiocarcinoma). "ASPSCR-1/Sirt-5 over-expression and siRNA knockdown experiments were employed for obtain of ASPSCR-1/Sirt-5 high or low expression (ASP-oe/Sirt5-oe or ASP-si/Sirt5-si) cholangiocarcinoma cell line (CCLP-1) cells." (PMID 37948465, 2023).
endotoxemia (2 papers, 2018 to 2021). "SIRT5+/+ and SIRT5−/− mice were subjected to endotoxemia induced by an i.p. challenge with 20 mg/kg LPS." (PMID 30515162, 2018). "In vitro studies using macrophages and splenocytes and preclinical models of endotoxemia and Gram-positive and Gram-negative bacteria infections suggest that SIRT5 deficiency has no major impact on antibacterial defenses." (PMID 30515162, 2018).
epileptic seizures (2 papers, 2016 to 2022). "Together, our findings indicate that SIRT5 deficiency strikingly increases susceptibility to KA-induced epileptic seizures by using different dosages of KA injection and different analyses of seizure severity." (PMID 27445698, 2016).
Glucose intolerance (2 papers, 2022 to 2024). Glucose intolerance (GI) can be defined as dysglycemia that comprises both prediabetes and diabetes. "Further, Sirt5-knockdown mice showed marked abnormalities in glucose and lipid metabolism, manifested by increased serum triglyceride and leptin levels, glucose intolerance, and decreased insulin sensitivity and adiponectin levels." (PMID 39408844, 2024). "Regarding the role of SIRT-5 in T2D, Wang and colleagues showed that SIRT-5 deficiency in brown adipose tissue (BAT) is followed by hyper-succinylation on GDH, SDHA, and UCP1, reducing their activity and causing glucose intolerance." (PMID 36080416, 2022).
Hyperammonemia (2 papers, 2025). An increased concentration of ammonia in the blood. "Methylmalonylation inhibits enzymes in the urea cycle and glycine cleavage pathway in MMA, while SIRT5 demalonylase activity effectively ameliorates hyperammonemia in MMA mice." (PMID 39979670, 2025). "SIRT5 regulates the clearance of ammonia by CPS1 and is regulated by PGC-1α, and activation of SIRT5 may contribute to the treatment of hyperammonemia." (PMID 39979670, 2025). "Furthermore, SIRT5 activates the key urea cycle enzyme CPS1 through deacetylation, enhancing ammonia detoxification, whereas SIRT5 deficiency compromises CPS1 activity and leads to hyperammonemia under stress conditions." (PMID 41301698, 2025).
intervertebral disc degeneration (2 papers, 2023 to 2025). "In the context of intervertebral disc degeneration, SIRT5 protects mitochondrial homeostasis via the desuccinylation modification of AIFM1." (PMID 40243486, 2025).
kidney injury (2 papers, 2020 to 2025). Trauma to the kidney. "Upregulation of SIRT5 expression alleviates septic acute kidney injury by enhancing AMPK phosphorylation." (PMID 39713961, 2025).
metabolic syndrome (2 papers, 2021 to 2025). A cluster of metabolic risk factors for CARDIOVASCULAR DISEASES and TYPE 2 DIABETES MELLITUS. "Small-molecule activators of SIRT5 (to increase malonylation removal) or agents that reduce malonyl-CoA levels in tissues (such as ACC inhibitors or MCD activators) could correct the excessive protein malonylation observed in metabolic syndrome." (PMID 41107644, 2025). "Indeed, SIRT5 inhibition by MC3482 might offer a novel pharmacological strategy to be considered in metabolic and cardiovascular rehabilitation programs to improve quality of life of obese subjects with T2D and metabolic syndrome." (PMID 34066961, 2021).
osteoarthritis (2 papers, 2022 to 2024). A noninflammatory degenerative joint disease occurring chiefly in older persons, characterized by degeneration of the articular cartilage, hypertrophy of bone at the margins and changes in the synovial membrane. "In addition, the Sirt5-Kma pathway may contribute to altered chondrocyte metabolism during osteoarthritis development since SIRT5-deficient chondrocytes exhibit increased Kma levels and decreased glycolysis and mitochondrial respiration rates." (PMID 35428309, 2022).
pancreatic ductal adenocarcinoma (2 papers, 2022 to 2023). An infiltrating adenocarcinoma that arises from the epithelial cells of the pancreas. "SIRT5 negatively regulates cancer cell proliferation in pancreatic ductal adenocarcinoma patients and is related to better prognosis." (PMID 37705968, 2023).
peritonitis (2 papers, 2018 to 2021). Inflammation of the peritoneum (tissue that lines the abdominal wall and covers most of the organs in the abdomen). "In a model of acute peritonitis induced by E. coli, bacterial dissemination into the blood (SIRT5+/+ vs. SIRT5−/−: 2.3 ± 1.3 × 108 CFU/ml vs. 3.8 ± 2.0 × 103 CFU/ml; mean ± SEM; P = 0.4) and mortality rate (73 vs. 91%, P = 0.6) were comparable using SIRT5+/+ and SIRT5−/− mice (plain lines)." (PMID 30515162, 2018).
pneumonia (2 papers, 2018 to 2021). An acute, acute and chronic, or chronic inflammation focally or diffusely affecting the lung parenchyma, caused by an infection in one or both of the lungs (by bacteria, viruses, fungi, or mycoplasma.). "SIRT5 deficiency did not worsen the outcome of mice in a quickly lethal model of S. pneumoniae-induced pneumonia." (PMID 30515162, 2018). "In a non-severe model of K. pneumoniae-induced pneumonia, body weight loss was similar in the SIRT5+/+ and SIRT5−/− groups." (PMID 30515162, 2018).
psoriasis (2 papers, 2021 to 2023). An autoimmune condition characterized by red, well-delineated plaques with silvery scales that are usually on the extensor surfaces and scalp. "To date, there have been few studies on the role of SIRT5 in psoriasis." (PMID 37445960, 2023). "There is a significant reduction in the expression of SIRT1, SIRT2, SIRT3, SIRT4 and SIRT5 and an increase in the expression of SIRT6 and SIRT7 in psoriasis." (PMID 37445960, 2023). "The dysregulation of this auto-regulatory loop could be also due to the abnormal expression of SIRTs in psoriasis, with the downregulation of SIRT1, SIRT2, SIRT3, SIRT4, and SIRT5 and upregulation of SIRT6 and SIRT7 in skin lesions skin, as previously reported." (PMID 34202251, 2021).
renal carcinoma (2 papers, 2021 to 2025). A carcinoma arising from the epithelium of the renal parenchyma or the renal pelvis. "Finally, we analyzed SIRT5 expression in renal cancer tissues and observed that it was significantly downregulated." (PMID 40858596, 2025).
retinal degeneration (2 papers, 2019 to 2022). Degeneration of the retina. "Sirt3 and Sirt5 double-knockout mice (Sirt3KO Sirt5KO) were strikingly more vulnerable to retinal degeneration upon light stress, as assessed by ERG, revealing important roles in photoreceptor survival." (PMID 35165261, 2022). "Moreover, we have previously reported that although mice lacking both SIRT3 and SIRT5 do not exhibit retinal degeneration at baseline, they are more vulnerable to light-induced degeneration." (PMID 30846716, 2019).
thyroid cancer (2 papers, 2023 to 2024). "Our results in breast and thyroid cancer cells show that SIRT5 activation, Pi binding or SIRT5 activation plus Pi binding greatly reduces cancer cell growth by impinging on autophagy and mitophagy and increasing ROS production." (PMID 37627630, 2023). "In this direction, our present results indicate that the use of a selective activator of sirtuin 5, called MC3138, alone or in association with a phosphate binder such as lanthanum acetate, can reduce cell viability, colony formation and mitophagy of breast and thyroid cancer cells." (PMID 37627630, 2023).
type 1 diabetes (2 papers, 2019 to 2020). "To test whether SIRT3 or SIRT5 exert a neuroprotective role under hyperglycemic conditions, we characterized whether germline deletion of Sirt3 or Sirt5 caused early neuroretinal dysfunction in a mouse model of type 1 diabetes." (PMID 30846716, 2019). "Therefore, we sought to determine whether combined deletion of both SIRT3 and SIRT5 may render mice more susceptible to retinal dysfunction in a model of type 1 diabetes." (PMID 30846716, 2019). "In this study, we investigated whether partially disrupting NAMPT-mediated NAD+ biosynthesis or deleting SIRT3/SIRT5 would accelerate early neuroretinal dysfunction in the STZ-induced mouse model of type 1 diabetes." (PMID 30846716, 2019). "The expression and activity of Sirt1, Sirt2, Sirt3, and Sirt5 is reduced in a streptozotocin- (STZ-) induced type 1 diabetes mellitus (T1DM) model, while the level of Sirt3 is increased in a high-fructose diet-induced T2DM model." (PMID 32256959, 2020). "Therefore, the motivation behind this study was to test whether there was a neuroprotective role for metabolic regulation via NAMPT-mediated NAD+ biosynthesis, SIRT3, or SIRT5 in a mouse model of type 1 diabetes." (PMID 30846716, 2019). "Moreover, SIRT3 and SIRT5 may have redundant roles in the inner retina and therefore possess the ability to functionally compensate for one another, as deletion of both was associated with modest, but significant, inner retinal dysfunction in the STZ-induced model of type 1 diabetes." (PMID 30846716, 2019). "The fact that monoallelic Nampt deletion did not accelerate retinal neurodegeneration in a mouse model of type 1 diabetes does not completely rule out the possibility that SIRT3 and SIRT5, downstream sensors of NAD+ availability, may still play a role in DR." (PMID 30846716, 2019).
uveal melanoma (2 papers, 2024 to 2025). A melanoma derived from melanocytes of the uveal tract. "Depletion of SIRT5 in vemurafenib-resistant cells inhibited cell proliferation, and caspase 3-dependent apoptosis was observed in several cutaneous and uveal melanoma cell lines upon SIRT5 suppression." (PMID 39935431, 2025).
adenovirus infection (1 paper, 2025). "RIP140 was overexpressed by adenovirus infection, and SIRT5 was overexpressed by plasmid transfection." (PMID 39968093, 2025).
aneurysm (1 paper, 2023). Bulging or ballooning in an area of an artery secondary to arterial wall weakening. "Our study found that abnormal expression of circ-ATL1, miR-455 and SIRT5 is correlated with the progression of IA in aneurysm patients." (PMID 36717793, 2023).
asthma (1 paper, 2023). "Consistent with animal data, Sirt1, Sirt3, and Sirt5 expression was decreased in the peripheral blood of patients with asthma compared to controls." (PMID 38135684, 2023).
bladder urothelial cancer (1 paper, 2020). "The same analysis was also performed in a TCGA bladder urothelial cancer cohort and a similar SIRTs expression profile was found, with IHG showing significantly increased SIRT4 expression levels comparing to PLG, whereas SIRT5 and SIRT6 expression levels were decreased." (PMID 32344886, 2020).
cardiomyopathy (1 paper, 2018). A disease of the heart muscle or myocardium proper. "SIRT5 gene (rank 945) was recently identified as an important regulator of cardiac function and is associated with cardiomyopathy in mice." (PMID 29311597, 2018).